STAT1 (signal transducer and activator of transcription 1)
Diseases named in the same sentence as STAT1 in open-access papers (continued):
Sharing a sentence is not in itself a finding about the gene and the disease.
infection (continued). "Consistently, immunoblotting analysis indicated that infection of LSDVΔ122 resulted in higher STAT1 and STAT2 phosphorylation upon IFN-β stimulation than wild-type LSDV." (PMID 41525414, 2026). "RNA velocity reconstruction showed that PMVECs transition from quiescent to activated transcriptional state upon infection, with Stat1 driving antigen-presenting gene induction." (PMID 41542053, 2026). "Regarding H820 cells, STAT1 and NF-κB were phosphorylated in basal conditions, during infection, and upon IFN treatment, although there was an increase in their levels during infection." (PMID 40434103, 2025). "Although the V protein of PIV5 dismantles IFN signalling by efficiently targeting STAT1 for degradation, the virus will still be exposed to ISGs upon infection of a cell already in an antiviral state." (PMID 40146622, 2025). "Both doses significantly activated the transcription of STAT1 and its downstream interferon-stimulated genes, while high-dose infection additionally triggered a cytokine storm characterized by excessive IL-6 and TNF-α expression." (PMID 40941331, 2025). "Activated STAT1 induces the expression of a series of ISGs at various stages of viral replication to combat infection." (PMID 40001503, 2025). "For example, PDL-1 expression is stimulated during infection by IFN signaling via the signal transducer and activator of transcription 1 (STAT1), potentially providing resistance to immune checkpoint blockade therapy." (PMID 40434103, 2025). "Volcano plots revealed that the most highly upregulated genes in response to OC43 infection, such as SOD2, CD44, STAT1 and MX1, were inflammation-associated genes and antiviral ISGs." (PMID 40368896, 2025). "Previous reports indicated that MACV is lethal in STAT-1−/− mice, with mice succumbing to infection 7–8 days post-challenge when the virus was administered by the IP route." (PMID 40733611, 2025). "The results demonstrated that total levels of STAT1 remained constant after 18 h of infection/treatment." (PMID 40521699, 2025). "IFITM3 expression was positively regulated by STAT1 during infection, whereas IFITM3 knockdown increased STAT1’s compensatory effect." (PMID 40681213, 2025). "As expected, compared with the ASFV-WT strain, ASFV-Δ4R infection increased phosphorylation of STAT1 and STAT2 and subsequent ISGF3 formation, leading to an elevated expression of antiviral gene ISGs." (PMID 40618140, 2025). "Of note, the cultures cluster derived from XX T21-12 specimen, which had lowest infection level, has consistently the highest STAT1 and STAT2 expression, corresponding to the highest MX1 expression." (PMID 40445428, 2025). "Consistently, phospho-STAT1 and total STAT1 protein levels increased toward the late stages of infection (20–24 h) in both cell types, reflecting active type I IFN signaling." (PMID 41346628, 2025). "Infection of both immunodeficient mice results in increases in viral RNA, but only Stat1 KO mice can develop inflammatory foci and have increased number of CD68 +cells in the heart tissue." (PMID 40304490, 2025). "IL-6, IL-1β, and STAT1 expression levels rapidly increased post-infection, peaking at 2 dpi with 11.84-fold, 13.22-fold, and 6.84-fold (all p < 0.05) elevation, respectively." (PMID 41011502, 2025). "Cytokines play an important role in resistance to T. gondii infection, and immune effector cells trigger the release of ROS through the IL-12-IFNγ-STAT1 pathway to clear the infection of T. gondii." (PMID 40005546, 2025). "Although the antiviral activity of STAT1 was seen in HepG2 cells transfected with the HBV genome, the viral products were decreased by small interfering RNA (siRNA) knockdown experiments of the STAT1 molecule in the infection system." (PMID 40048440, 2025).
infection (continued). "Multiple STAT family members were activated during E. chaffeensis infection, including STAT1, STAT3, STAT5, and STAT6; however, using a specific STAT3 inhibitor, most of STAT-related gene expression during infection was found to be associated with STAT3." (PMID 41115066, 2025). "Between 12 h and 24 h after FMDV infection, p-STAT1 was found in both wild-type and PLA2G16-overexpressing cells; the phosphorylated STAT1 levels in the PLA2G16-overexpressing cells were noticeably higher than in the wild-type cells." (PMID 40733501, 2025). "Subsequent observation indicated that following PolyI:C treatment, infection with L. major resulted in the inhibition of nuclear translocation of STAT1 in a PKR-dependent manner and consequently affected the PKR promoter occupancy." (PMID 40521699, 2025). "In conclusion, we report a novel STAT1−/− model of MACV disease that results in fully lethal infection and recapitulates many aspects of disease in NHPs and humans." (PMID 40733611, 2025). "While phosphorylated STAT1 levels in wild-type cells started to decline as early as 16 h after infection, STAT1 phosphorylation levels in PLA2G16-overexpressing cells continuously increased from 12 h to 24 h following FMDV infection." (PMID 40733501, 2025). "Immunoblot analysis demonstrated that the knockout of STUB1 blocked the Sec10-mediated degradation of STAT1 and inhibition of p-STAT1 upon infection with VSV or HSV-1." (PMID 40920886, 2025). "ANDV infection of pulmonary endothelial cells also showed strong upregulation of phospho-STAT1 on Western blot, suggesting robust induction of type I IFN signaling and interferon-stimulated genes (ISGs)." (PMID 40857262, 2025). "Our results also suggest the importance for the innate immune response to VA1 infection as we observed higher quantities of VA1 RNA in Stat1 KO mice compared to WT mice." (PMID 40304490, 2025). "The smallest p-adjusted value for either group was STAT1, with genes involved in immunological signaling, inflammation, and interferon response following infection." (PMID 38932113, 2024). "Our results showing lower JAK2 and STAT1 expression levels during infection prompted us to determine if this required chlamydial protein synthesis." (PMID 39194253, 2024). "It is reasonable that during late infection, accumulation of dsRNA generated by viral replication triggers apoptosis to cleave STAT1." (PMID 38018976, 2024). "At 36 h post-infection, the infected cells were treated with the inhibitors for another 12 h, and the expression of STAT1 was examined." (PMID 38018976, 2024). "We observed significantly increased expression of TNF-α, IL8, MCP, and STAT1 genes in trained macrophages upon infection by both the Mtb strains, similar to those observed in trained and restimulated macrophages." (PMID 38980014, 2024). "IF staining of mouse brains at day 7 post-infection showed that the levels of p-STAT1, IRF1, and PD-L1 in Ifnar1−/− and Ifngr1−/− mice were lower than those in control littermates." (PMID 38715061, 2024). "For instance, the pandemic influenza A (H1N1) 2009 virus (pH1N1) infection exhibited dose- and time-dependent activated STAT1, and high-dose infection induced robust and earlier activation." (PMID 39769350, 2024). "The previous report has demonstrated that IBV inhibits IFNβ-mediated nuclear translocation of STAT1 at the late stages of infection." (PMID 39602452, 2024). "Western blot analysis indicated the presence of elevated phosphorylated-STAT4 (pSTAT4) and phosphorylated-STAT1 (pSTAT1) levels at 8, 12, and 24 hours post-infection." (PMID 39119293, 2024). "Nevertheless, unphosphorylated STAT1 inhibits macrophage apoptosis, promoting Mtb immune evasion and helping Mtb to persist in infection." (PMID 38615114, 2024).
infection (continued). "Reduction of STAT1 phosphorylation correlated with reduced STAT1 nuclear translocation during BA.4 and BA.5 infection compared with BA.2, measured by high-content single-cell immunofluorescence imaging of infected nucleocapsid-positive Calu-3 cells." (PMID 38228858, 2024). "ASFV-intB318L infection also obviously suppressed the phosphorylation and nuclear translocation of STAT1 and STAT2; the inhibitory effect was significantly lower than that of ASFV-WT infection." (PMID 38620034, 2024). "We observed an infection-dependent decrease in STAT1 transcript as early as 8 to 16 hpi in infected cells and a decrease in JAK2 between 16 and 24 hpi." (PMID 39194253, 2024). "We found that the type I interferon (IFN-I)-related genes, DDX60, IFI16, IRF7, ISG15, OAS1, and STAT1, were more highly expressed after Omicron breakthrough infection." (PMID 39835127, 2024). "Once in the nucleus, the STAT1 homodimer complex binds to gamma-activated site promoter elements to drive expression of a subset of ISGs meant to impede the infection." (PMID 38712050, 2024). "Meanwhile, mice that lack STAT1 signaling in CD11c+ cells were unable to control disseminated infection." (PMID 39324785, 2024). "STAT1-KO (C57BL/6-STAT1−/−) mice are known to be a useful mouse model for studying the mechanisms of IFN-induced and STAT1-dependant resistance to infection and disease." (PMID 38287325, 2024). "This indicates that the observed phenotype of STAT1 and STAT2 cleavage and degradation in SVA infection is caused by 3Cpro." (PMID 38869319, 2024). "1/3 IFNAR-/- mice became viremic with RPgV, while 0/3 IFNGR-/- and 0/3 IFNAGR-/- mice became infected, suggesting that PgV cross-species infection is restricted by type-I-IFN/Stat-1 signaling." (PMID 39196893, 2024). "We found that ASFV-WT infection significantly reduced the phosphorylation and nuclear translocation of STAT1 and STAT2 induced by IFN-α." (PMID 38620034, 2024). "Our data indicate that infection with the isoniazid-resistant M. tuberculosis strain preferentially resulted in cGAS-STING/STAT1 activation, which induced a characteristic host immune response." (PMID 39597535, 2024). "STAT phosphorylation is a dynamic modification; preliminary testing suggested STAT3 was maximally phosphorylated at early times post infection (0.5 hpi) while STAT1 maximum phosphorylation occurred at 24 hpi." (PMID 38768227, 2024). "If this IL-24-mediated tissue injury response is analogous to pathogen infection where IFNs are upstream of STAT1/2, then IL-24 should be important for STAT3 activation in wounds." (PMID 37098344, 2023). "CCD-18Co normal colon fibroblasts were used, and we found that both M1-GFP and M1-NS3M significantly activated PKR and STAT1 at 24 h after infection, resulting in intense inhibition of viral replication." (PMID 37296165, 2023). "If STAT1-dependent expression of ISGs is required to restrict infection in cells with reduced p38β expression, deletion of STAT1 would restore SARS-CoV-2 replication to wild-type levels." (PMID 37345956, 2023). "At 12 h post-infection, the nuclear expression levels of p-STAT1 were similar between cells infected with rIBV and rIBV-ΔPL1pro-N." (PMID 38087313, 2023). "The molecularly defined IEI associated with severe or disseminated cryptococcosis strikingly overlap with those that predispose one to infection with TDEF, namely, MSMD, GATA2, CD40L deficiency, STAT1 GOF, and DN-STAT3; these IEI have been detailed above." (PMID 36986378, 2023). "First, ASPP2 is a transcriptional target of STAT1, a transcription factor that is activated upon infection." (PMID 37750869, 2023). "Accordingly, at 7-hr post infection, we were able to capture clusters of STAT1/STAT2 translocated cells." (PMID 36629318, 2023). "STAT1 phosphorylation in CD8+ T-cells was analyzed 24 h post-LM-OVA infection, as a read-out of IFN-γ signaling." (PMID 37872155, 2023).
infection (continued). "In blood neutrophils, in the steady state (e.g. Myc, H2-DMb2, H2-M3, H2-Q7...) but also during infection e.g. Cxcl10, H2-D1, C4a, Psme1, Stat1, Psme2, more genes were upregulated in neutrophils from female mice." (PMID 38179044, 2023). "Consistent with being lytically infected, GFP+ red pulp FC sorted from WT and Stat1−/− mice 22 h post infection expressed high levels of ie1/ie3, M38 and M48(SCP) transcripts." (PMID 37248241, 2023). "As expected, infection with EBOV WT almost completely prevented STAT1 nuclear localization, whereas infection with the mutants resulted in detectable STAT1 nuclear localization." (PMID 37243162, 2023). "SARS-CoV ORF6 regulates the IFN signaling, since infection with SARS-CoV blocks the nuclear trafficking of STAT1 in Vero cells transfected with STAT1-GFP, in contrast to deletion mutants lacking ORF6." (PMID 37197199, 2023). "Infection of fibroblasts and epithelial cells with the high-passage HCMV strain, Towne, causes proteasomal degradation of JAK1 to terminate phosphorylation of STAT1." (PMID 37289831, 2023). "After a high-MOI infection, nearly all bystander cells display p-STAT1 already at 10 h p.i., but also very likely have a virus-infected neighbor." (PMID 37669278, 2023). "Using transgenic mice, we demonstrate that T cell intrinsic STAT1 signaling is required to curb inflammation during acute infection with Toxoplasma gondii." (PMID 37559725, 2023). "This difference was not present at the onset as indicated by the undiminished viral genomic loads in both GFP+ and GFP- red pulp FC from Stat1−/− mice at 22 h post infection." (PMID 37248241, 2023). "Both MiR-155-5p and STAT1 are regulated by positive feedback in response to inflammatory signals or infection." (PMID 38098120, 2023). "This was accompanied by a diminishment in total STAT1 levels in ΔUL138STOP infection to resemble uninfected cells, whereas STAT1 remained elevated in WT infection." (PMID 37289831, 2023). "The STAT1 protein helps keep the immune system in balance by controlling the IL-17 pathway which promotes inflammation during infection and promotes tissue repair." (PMID 38133335, 2023). "These most variably expressed VE genes, including STAT1, are likely relevant to inter-individual variability following infection of AMs." (PMID 37333188, 2023). "Interferons increase hematopoietic stem cells during infection by activating STAT1, but the mechanisms by which STAT1 regulates intrinsic programs in neural stem cells (NSCs) during neuroinflammation is less known." (PMID 37663126, 2023). "For instance, infection with type I strain (BK) has been found to suppress the tyrosine phosphorylation of STAT1 in host cells." (PMID 38003154, 2023). "In sum, the findings of this study significantly broaden our understanding of the functions of murine STAT1 during in vivo infection with a β-herpesvirus." (PMID 37248241, 2023). "In the transcriptome results of this study, the encoding genes of BST2, STAT1, and hnRNPA1 were only upregulated in the PEDV 85-7C40 infection process." (PMID 35762780, 2022). "NSP5 promotes the autophagic degradation of STAT1, evident by decreased nuclear translocation and protein levels of STAT1 upon infection." (PMID 36146796, 2022). "While the regulators NLRC5, IRF1, STAT1, and HLA-B were progressively activated through the infection time course in B.6 and B.1.1.8 infections, they were hardly detected in Delta infection." (PMID 36073824, 2022). "It has been recently documented that formulation of ML29 with DIPs resulted in complete attenuation of ML29 infection in STAT1-/- mice." (PMID 36289695, 2022). "Despite the STAT1-dependency of these antigen presentation molecules, we quantified no impairment in T cell activation at multiple time-points during infection in MGSTAT1Δ mice." (PMID 36067217, 2022). "STAT1 phosphorylation in B.6 and B.1.1.8 infections by 24 hpi confirmed IFN-mediated activation of the JAK-STAT pathway." (PMID 36073824, 2022).
infection (continued). "STAT1−/− and STAT4−/− mice infected with LmexWT showed significant footpad swelling starting at 2 weeks post-infection (wpi) for STAT1−/−, and at 3 wpi for STAT4−/−." (PMID 35236861, 2022). "Treatment of mice with IFNλ reduced infection burden and protected immunocompromised mice from severe outcomes including death, with effects that required STAT1 signaling in the enterocyte." (PMID 35584177, 2022). "We quantified this effect by looking directly at the presence of viral proteins as the definite manifestation of productive infection and at nuclear p-STAT1 as an indication of antiviral alertness." (PMID 36326278, 2022). "In contrast, we found six proteins altered by infection with CoV-2(B), among which five were downregulated (i.e., STAT1, HLA-E, TPR, TRIM25, and TRIM28)." (PMID 36175400, 2022). "Extracts from two herbs, including a natural extract from Gardenia jasminoides J. Ellis (GJ-4) and bisabolane-type sesquiterpenoids isolated from turmeric, were mentioned here to antagonize Alzheimer’s disease (AD) and infection through inactivating STAT1." (PMID 36324680, 2022). "The response of infection, in macrophages, occurs due to the activation of different transcription factors (TFs), such as STAT1, IRF, NF-κB, and STAT6." (PMID 35774406, 2022). "The converse was observed in the COA3 and COA6 PDXs, in which STAT1 expression decreased with M002 infection." (PMID 35159029, 2022). "Upon infection with SeV, confirmed by the increase in p-STAT1, peroxisomal MAVS oligomers appear at the higher density fraction." (PMID 35445031, 2022). "In the trachea, expression of PRRs, ISGs, IRF7 and STAT1 were moderately up regulated in both groups during the course of infection." (PMID 34918620, 2022). "The human Coronavirus OC43 (HCoV-OC43) infection can specifically reduce STAT1 and STAT3 phosphorylation." (PMID 35456913, 2022). "Our results derived from the infection of Stat1ΔIEC animals uncovered the manifold role of intestinal STAT1 signaling for the control of Caspase-dependent and -independent cell death." (PMID 34497340, 2022). "The protective role of IFN-I against CCHFV has been exemplified in animal models in which IFNAR−/− or STAT-1−/− mice or STAT2−/− hamsters showed enhanced susceptibility to CCHFV-infection." (PMID 35437144, 2022). "Knockdown of BCLAF1 led to decreased STAT1 and STAT2 phosphorylation, and increased susceptibility to infection by alphaherpesvirus in lung and brain tissue of mice." (PMID 35803911, 2022). "STAT1 is also a critical transcription factor involved in many physiological functions, including the response to infection." (PMID 36185646, 2022). "Taken together these data suggested that LgyLRV1+ infection of murine BMDMs resulted in activation of the STAT-1 and NF-kB pathways where the latter is controlled or insufficient to produce large amounts of NO to control infection." (PMID 36034693, 2022). "Delta infection delayed STAT1 phosphorylation until 72 hpi, while Alpha induced a modest and steady phosphorylation after 24 hpi." (PMID 36073824, 2022). "Nuclear factor-kappa B (NF-κB) and signal transducer and activator of transcription 1 (STAT1) impact on M1 polarization are involved in the infection progress." (PMID 36619996, 2022). "Recently, we have documented that CD8 T cells play a critical role in pathogenicity during the acute phase of LASV infection in STAT1-/- mice, while CD4 T cells play an important role in LASV-induced hearing loss during the chronic phase of infection." (PMID 36289695, 2022). "Upon infection, the expression of STAT1 gene was highly upregulated, and the DoD value of STAT1 TAD was decreased." (PMID 36195603, 2022). "We found that infection with either of these viruses inhibits signaling from the IFN receptor by inhibiting STAT1 phosphorylation and nuclear localization." (PMID 35720342, 2022). "In this assay, VSV titers in infected patient EBV-B cells were comparable to STAT1-deficient EBV B-cells after 24h and 48h of infection." (PMID 36159783, 2022).